EGFR (epidermal growth factor receptor)
Diseases named in the same sentence as EGFR in open-access papers (continued):
Sharing a sentence is not in itself a finding about the gene and the disease.
metastatic colorectal cancer (continued). "For example, the PDX-IM model of 85 patients with metastatic colorectal cancer was established to predict resistance to targeted anti-EGFR therapies using a combination of anti-HER-2 and anti-EGFR therapies." (PMID 37344821, 2023). "For metastatic colorectal cancer (CRC), drugs targeting the epidermal growth factor receptor (EGFR), such as cetuximab and panitumumab, have been recommended, but patients with KRAS mutations are unresponsive to them and have no other options." (PMID 36768973, 2023). "Cetuximab, a monoclonal antibody targeting epidermal growth factor receptor (EGFR), is effective for RAS wild-type metastatic colorectal cancer (mCRC) patients." (PMID 36609651, 2023). "The standard systemic medication for metastatic colorectal cancer and metastatic gastrointestinal cancer includes cytotoxic drugs (for example, oxaliplatin or bevacizumab) and/or targeted agents (anti-VEGFR, anti-EGFR antibodies)." (PMID 38139437, 2023). "Targeted therapy targeting the EGFr and vascular endothelial growth factor (VEGF) is often combined with chemotherapy in palliative treatment of metastatic colorectal cancer." (PMID 37296984, 2023). "In many countries, EGFr- and VEGF-targeted therapies are introduced in the first-line setting of metastatic colorectal cancer." (PMID 37296984, 2023). "This Phase I/II study examined the toxicity and efficacy of high-dose pulsed AZD8931, an EGFR/HER2/HER3 inhibitor, combined with chemotherapy, in metastatic colorectal cancer (CRC)." (PMID 36352028, 2023). "Epidermal growth factor receptor (EGFR) inhibitors, panitumumab, and cetuximab used to treat metastatic colorectal cancer expressing wild-type KRAS show a beneficial effect in only 10–20% of patients." (PMID 36013252, 2022). "Anti-epidermal-growth-factor-receptor (EGFR) monoclonal antibodies (mAbs) are of great significance for RAS and BRAF wild-type metastatic colorectal cancer (mCRC) patients." (PMID 36131281, 2022). "Current FDA-approved medications for the treatment of metastatic colorectal cancer include two monoclonal antibodies (cetuximab, panitumumab) that selectively inhibit EGFR (epidermal growth factor receptor)." (PMID 35685436, 2022). "The first-line chemotherapy for patients with RAS and BRAF wild-type metastatic colorectal cancer (mCRC) commonly involves cytotoxic regimens, such as FOLFOX and FOLFIRI, combined with epidermal growth factor receptor (EGFR) antibodies." (PMID 36439491, 2022). "The anti-epidermal growth factor receptor (EGFR) antibodies (i.e., cetuximab and panitumumab) have a key role in the treatment of metastatic colorectal cancer." (PMID 35530345, 2022). "Combination treatment of anti-EGFR and anti-VEGF drugs in patients with metastatic colorectal Cancer." (PMID 34109130, 2021). "Patient selection for addition of anti-EGFR therapy to chemotherapy for patients with RAS and BRAF wildtype metastatic colorectal cancer can still be optimised." (PMID 34253874, 2021). "This included 363 patients with unresectable or metastatic colorectal cancer and compared the combination of MEK inhibitor and PD-L1 inhibitor against PD-L1 inhibitor alone or regorafenib (EGFR/VEGF inhibitor)." (PMID 34298779, 2021). "In the EGFR-related signaling pathway, PI3K/Akt, MAPK, and mTor were involved in metastatic colorectal cancer." (PMID 34067437, 2021). "Cetuximab and panitumumab, as the highly effective antibodies targeting epidermal growth factor receptor (EGFR), have clinical activity in the patients with metastatic colorectal cancer (mCRC)." (PMID 32665850, 2020). "Erbitux, for example, recognizes and blocks the epidermal growth factor receptor (EGFR) and is FDA approved for the treatment of metastatic colorectal cancer." (PMID 31783651, 2019). "RAS genotyping is mandatory to predict anti-EGFR monoclonal antibodies (mAbs) therapy resistance and BRAF genotyping is a relevant prognosis marker in patients with metastatic colorectal cancer." (PMID 31068650, 2019).
metastatic colorectal cancer (continued). "Monoclonal antibodies against the epidermal growth factor receptor (EGFR), including cetuximab and panitumumab, have been used to treat patients with metastatic colorectal cancer." (PMID 31711486, 2019). "Anti-epidermal growth factor receptor (EGFR) antibodies, panitumumab (Pmab) and cetuximab (Cmab), are widely used for patients with wild-type (WT) KRAS metastatic colorectal cancer." (PMID 30290786, 2018). "Epidermal growth factor receptor (EGFR) - targeted monoclonal antibodies (MAb), such as cetuximab and panitumumab, have been used in the treatment of metastatic colorectal cancer (mCRC) since 2004." (PMID 29765524, 2018). "MET amplification is rare in treatment-naïve metastatic colorectal cancer (CRC) tumors, but can emerge as a mechanism of resistance to anti-EGFR therapies." (PMID 30211110, 2018). "Monoclonal antibodies (mAb) targeting the epidermal growth factor receptor (EGFR), cetuximab and panitumumab, have been approved for the treatment of RAS wild-type metastatic colorectal cancer (CRC)." (PMID 30410004, 2018). "Panitumumab is a fully humane monoclonal antibody targeting the epidermal growth factor receptor (EGFR) and is registered for the treatment of RAS wild-type metastatic colorectal cancer, either alone or combined with chemotherapy." (PMID 29170802, 2018). "Panitumumab, a fully human monoclonal antibody specific to the EGFR, has been approved by the FDA for the treatment of EGFR-expressing metastatic colorectal cancer with disease progression." (PMID 28125617, 2017). "Epidermal growth factor receptor (EGFR)-targeted monoclonal antibodies (mAbs), such as panitumumab and cetuximab, have had an impact on metastatic colorectal cancer therapy." (PMID 28159933, 2017). "This meta-analysis compared anti-EGFR to anti-VEGF therapy when combined with FOLFIRI or FOLFOX chemotherapy, as first-line treatment for advanced or metastatic colorectal cancer." (PMID 29029527, 2017). "Anti-EGFR mAbs cetuximab and panitumumab are routinely used for the treatment of patients with KRAS-wild type metastatic colorectal cancer (mCRC)." (PMID 28032593, 2017). "In metastatic colorectal cancer, amplification and overexpression of MET is a key contributing factor to resistance to anti-EGFR therapies." (PMID 28388297, 2017). "For example, patients with metastatic colorectal cancer who have KRAS mutations would not be expected to respond to anti-EGFR therapies such as cetuximab, whereas patients with metastatic melanoma who have a BRAF mutation may be suitable for anti-BRAF therapies such as vemurafenib and dabrafenib." (PMID 28114309, 2017). "An example is the combination of anti-epidermal growth factor receptor (EGFR) antibodies (cetuximab or panitumumab), anti-vascular endothelial growth factor (VEGF) antibody (bevacizumab), and chemotherapy in metastatic colorectal cancer." (PMID 27793177, 2016). "Our data provide a new mechanism-based rationale supporting clinical trials testing the strategy of EGFR and COX-2 dual blockade for treating metastatic colorectal cancer." (PMID 27074568, 2016). "Chemotherapy and novel biologics targeting the epidermal growth factor receptor (EGFR) and vascular endothelial growth factor (VEGF) pathways have been the mainstay to treat advanced or metastatic colorectal cancer (mCRC)." (PMID 27463016, 2016). "Our results provide important mechanistic data supporting dual targeting of EGFR and COX-2 as a rational approach for treating metastatic colorectal cancer." (PMID 27074568, 2016). "Angiogenesis and epidermal growth factor receptor (EGFR) inhibition has been shown to have anti-tumour efficacy, and enhance the therapeutic effects of cytotoxic chemotherapy in metastatic colorectal cancer." (PMID 26517691, 2015). "Cetuximab, a chimeric human-mouse monoclonal antibody to the epidermal growth factor receptor (EGFR), has shown clinical efficacy in individuals with metastatic colorectal cancer (mCRC)." (PMID 25474137, 2014).
metastatic colorectal cancer (continued). "Advances have been made in the last years in metastatic colorectal cancer treatments, with the introduction of novel molecularly targeted agents like antibodies against the VEGF or the EGFR targets; nonetheless rate of long survivors are low." (PMID 24497922, 2014). "Panitumumab is a full human epidermal growth factor receptor (EGFR) monoclonal antibody, an agent for metastatic colorectal cancer therapy." (PMID 24517087, 2014). "Epidermal Growth Factor Receptor (EGFR) inhibitors, such as cetuximab and panitumumab, have shown survival benefit in combination with chemotherapy and as monotherapy in metastatic colorectal cancer (mCRC) patients." (PMID 25375154, 2014). "Cetuximab and panitumumab are antibodies that target the epidermal growth factor receptor (EGFR) and are currently part of standard regimens against metastatic colorectal cancer with wild-type (WT) K-Ras." (PMID 23918228, 2013). "Cetuximab targets the epidermal growth factor receptor (EGFR) and is used in KRAS-wild type, metastatic colorectal cancer." (PMID 23286345, 2013). "Cetuximab and panitumumab are the two anti-EGFR mAbs that have demonstrated clinical benefit and have gained FDA approval for the palliative treatment of chemotherapy resistant wtKRAS metastatic colorectal cancer (mCRC)." (PMID 23091721, 2012). "This suggests that future studies should examine specific mechanism escape for EGFR and VEGFR inhibition to design biology-driven approaches for improved therapy in metastatic colorectal cancer." (PMID 22701615, 2012). "Cetuximab, a chimeric monoclonal antibody targeting the epidermal growth factor receptor (EGFR), has demonstrated efficacy and overall survival benefits in patients with K-Ras wild-type metastatic colorectal cancer." (PMID 21629245, 2011). "Since 2004, numerous studies have demonstrated the efficiency of monoclonal antibodies (mAbs) targeting the epidermal growth factor receptor (EGFR) ectodomain, such as cetuximab and panitumumab, in patients with metastatic colorectal cancer (MCRC)." (PMID 21139621, 2010). "Resistance to anti-epidermal growth factor receptor (EGFR) monoclonal antibodies (mAb) is common in metastatic colorectal cancer (mCRC) and reliable predictive biomarkers remain lacking." (PMID 42027771, 2026). "Given the lack of prior studies on circ-EGFR expression and cetuximab response in metastatic colorectal cancer (mCRC), we first undertook these experiments in a clinical trial cohort of patients with mCRC." (PMID 41214390, 2025). "Cetuximab, an epidermal growth factor receptor (EGFR) inhibitor that belongs to the monoclonal antibody class, is widely used to treat head and neck squamous cell carcinoma and in patients with RAS wild-type metastatic colorectal cancer." (PMID 41458789, 2025). "The most effective chemotherapy regimens used in the metastatic colorectal cancer setting involve combinations of a fluoropyrimidine with oxaliplatin or irinotecan and a monoclonal antibody targeting VEGF or, in patients with wild-type KRAS, targeting EGFR." (PMID 40004631, 2025). "Taken together, these data demonstrate that circ-EGFR enhances cetuximab sensitivity in CRC cells, suggesting that circ-EGFR may be a potential predictor of cetuximab response in metastatic colorectal cancer (mCRC)." (PMID 41214390, 2025). "Epidermal growth factor receptor (EGFR) inhibitors are used to treat some patients with metastatic colorectal cancer, but many tumors do not respond or develop resistance during therapy." (PMID 40940901, 2025). "Mutations of the BRAF gene are a negative predictor for anti‐EGFR treatment response and indicators of poor prognosis in metastatic colorectal cancer (mCRC)." (PMID 40302146, 2025). "The paradigm of molecular negative hyperselection, beyond RAS and BRAF, identifies metastatic colorectal cancer (mCRC) patients with the greatest benefit from anti-epidermal growth factor receptor (anti-EGFR) agents." (PMID 41167084, 2025).
metastatic colorectal cancer (continued). "Initially, HER2 was identified as a negative predictive biomarker in metastatic colorectal cancer (mCRC), its amplification or overexpression correlating with resistance to anti-EGFR treatments." (PMID 39682117, 2024). "Recommended first and second line treatments for unresectable metastatic colorectal cancer (mCRC) include fluorouracil-based chemotherapy, anti-vascular endothelial growth factor (VEGF)-based therapy, and anti-epidermal growth factor receptor-targeted therapies." (PMID 39325367, 2024). "Monoclonal antibodies targeting EGFR, either when combined with conventional cytotoxic chemotherapy, or as single agents, produce significant survival prolongation in patients with RAS and BRAF wild type metastatic colorectal cancer (mCRC)." (PMID 36352028, 2023). "The EGFr-targeted drug cetuximab demonstrates clinical efficacy in first-, second-, and third-line treatment alone or in combination with chemotherapy in patients with RAS wild-type metastatic colorectal cancer." (PMID 37296984, 2023). "Cetuximab, a monoclonal antibody that binds the extracellular domain of epidermal growth factor receptor (EGFR), is effective in KRAS wild-type metastatic colorectal cancers but not in KRAS mutations." (PMID 37513471, 2023). "This study demonstrated that skin toxicity is not a predictor of OS and PFS in patients with metastatic colorectal cancer treated with anti-EGFR inhibitors." (PMID 36980549, 2023). "The first-line therapy of patients with RAS wild-type (WT) non-resectable metastatic colorectal cancer (mCRC) is usually 5-fluorouracil-based chemotherapy with either bevacizumab or an anti-epidermal growth factor receptor (EGFR)." (PMID 35326562, 2022). "In patients with metastatic colorectal cancer, BRAF-mut portends a significantly worse prognosis, and is associated with both a lack of response to anti-EGFR therapy and a decreased resectability rate of recurrence after the initial resection of CLMs." (PMID 36013567, 2022). "In metastatic colorectal cancer (mCRC), the ORR to BRAFi and BRAFi/MEKi combinations is much lower, <15% in some trials, and well-characterized BRAFi resistance mechanisms in mCRC include bypass signaling via epidermal growth factor receptor (EGFR)." (PMID 35486732, 2022). "Monoclonal antibodies targeting the epidermal growth factor receptor (EGFR), including cetuximab and panitumumab, were effective against metastatic colorectal cancer, and GC1118 (a novel, fully humanized anti-EGFR IgG1 antibody) alone had a better antitumor effect." (PMID 34706700, 2021). "Epidermal growth factor receptor (EGFR) inhibitors like panitumumab and cetuximab are already approved for the treatment of RAS wild-type metastatic colorectal cancer, but their role in LARC remains unclear." (PMID 34684080, 2021). "The best studied reactions are immediate anaphylactic reactions following first-time intravenous administration of cetuximab, a chimeric mouse-human monoclonal IgG antibody against the epidermal growth factor receptor (EGFR), which is applied in patients with metastatic colorectal cancer." (PMID 35386980, 2021). "The introduction of targeted therapies, especially monoclonal antibodies targeting epidermal growth factor receptor (EGFR), such as cetuximab, a human-mouse chimeric IgG1 antibody, in the treatment of patients with metastatic colorectal cancer (mCRC), has led to a consistent improvement in survival." (PMID 34211852, 2021). "Extensive research efforts have been focused on EGFR over the past two decades and anti-EGFR therapy in combination with conventional chemotherapy is now in routine practice for cancers such as metastatic colorectal cancer (mCRC)." (PMID 33007872, 2020). "In wild-type (wt) RAS metastatic colorectal cancer (mCRC), the emergence of RAS mutant clones under the selective pressure of epidermal growth factor receptor (EGFR) inhibitors has been widely described, providing a molecular rationale for liquid biopsy-based adaptive therapies." (PMID 33291569, 2020).
metastatic colorectal cancer (continued). "Patients with metastatic colorectal cancer (mCRC), harboring RAS mutations, do not benefit from anti‐epidermal growth factor receptor (EGFR) monoclonal antibodies (MoAbs) such as cetuximab and panitumumab." (PMID 31350822, 2019). "Moreover, our data may shape our ideas about re-sensitizing RAS mutant tumors toward EGFR inhibition and opens up new perspectives for designing more resistance preventive treatment approaches such as drug holiday concepts for patients with metastatic colorectal cancer." (PMID 32039027, 2019). "Infusion reactions and hypersensitivities have been reported among metastatic colorectal cancer patients treated with anti‐EGFR therapies, but the summary incidence has not previously been characterized." (PMID 31376243, 2019). "Cetuximab and panitumumab are two distinct monoclonal antibodies (mAbs) targeting the epidermal growth factor receptor (EGFR), and both are widely used in combination with chemotherapy or as monotherapy to treat patients with RAS wild-type metastatic colorectal cancer." (PMID 31616627, 2019). "For metastatic colorectal cancer, the likely consequence of a false negative result is that a patient inappropriately receives anti-EGFR treatment." (PMID 30092778, 2018). "For instance, Symphogen A/S has developed Sym004, which is currently being evaluated in a clinical trial phase II as a mixture (1:1) of 2 chimeric IgG1 Abs (mAb992 and mAb1024 against nonoverlapping epitopes on EGFR to target metastatic colorectal cancer)." (PMID 30176252, 2018). "This meta-analysis compares anti-EGFR (cetuximab, panitumumab) therapies to anti-VEGF (bevacizumab) therapies when combined with FOLFIRI or FOLFOX chemotherapy, as first-line treatment for advanced or metastatic colorectal cancer." (PMID 29029527, 2017). "In patients with metastatic colorectal cancer, KRAS mutation is a negative predictive marker for anti-EGFR therapy." (PMID 29228748, 2017). "However, targeted treatment, such as anti-epidermal growth factor receptor (EGFR) and anti-vascular endothelial growth factor (VEGF) therapies, have had a relatively minor effect on the survival of metastatic colorectal cancer patients." (PMID 28784136, 2017). "Approximately 30% of patients with wild type RAS metastatic colorectal cancer are non-responders to anti-epidermal growth factor receptor monoclonal antibodies (anti-EGFR mAbs), possibly due to undetected tumoral subclones harboring RAS mutations." (PMID 27916952, 2016). "Tumor budding was predictive for non-response to anti-EGFR therapies in metastatic colorectal cancer patients." (PMID 27861522, 2016). "Cetuximab, a mouse-human chimeric antibody that binds to the extracellular domain of EGFR and blocks ligand-induced activation of EGFR, has been approved by the US Food and Drug Administration (FDA) for treatment of metastatic colorectal cancer and metastatic head and neck cancer." (PMID 27074568, 2016). "KRAS mutations are an established predictor of lack of response to EGFR-targeted therapies in patients with metastatic colorectal cancer (mCRC)." (PMID 27636997, 2016). "EGFR therapeutic antibodies such as cetuximab and panitumumab can inhibit the binding of ligands to EGFR and suppress EGFR signaling, and have been approved by the FDA for the treatment of head and neck cancer and metastatic colorectal cancer." (PMID 25960704, 2015). "Therefore, the interplay between EGFR signaling and CIP2A in metastatic colorectal cancer warrants further investigation." (PMID 25896895, 2015). "The aim of our study was to investigate whether microRNAs (miRNAs) could serve as predictive biomarkers to anti-EGFR therapy (cetuximab, panitumumab) in patients with RAS wild-type (wt-RAS) metastatic colorectal cancer (mCRC)." (PMID 26497852, 2015). "Mutations in KRAS and NRAS genes are negative predictors of anti-EGFR therapies response in metastatic colorectal cancer." (PMID 25859555, 2015).